CD14 (CD14 molecule)
Diseases named in the same sentence as CD14 in open-access papers (continued):
Sharing a sentence is not in itself a finding about the gene and the disease.
tumor (continued). "Tumor immune cells (PTPRC/CD45+) also consisted of B cells (MS4A1/CD20+), plasma cells (XBP1+), macrophages (CD14+), dendritic cells (CD80+, CD86+), and mast cells (TPSAB1+)." (PMID 35742914, 2022). "Despite a wide array of evidence supporting a predominant role of cDC1s in anti-tumor immunity, CD1c+ CD14− cDC2s also participate by infiltrating tumors and triggering CD4+ T cell responses at tumor draining lymph nodes." (PMID 36230990, 2022). "The results demonstrated significantly higher numbers of CD14+ and CD68+ cells in the tumour infiltrate of PDLIM2-positive tumours and in PDLIM2-positive stroma than in either PDLIM2-negative tumours or stroma." (PMID 36531051, 2022). "the appearance of the CD14 and DC-SIGN double-positive population is a unique feature of the tumor-driven differentiation." (PMID 36194602, 2022). "CD14+ cells from tumour tissue have higher expression of the macrophage markers CD68, CD206 and CD163 but only CD163 was increased in patient blood CD14+ cells." (PMID 34727230, 2022). "At 72 h, colon and tumour tissue were collected and examined for histopathological changes and RT-PCR for genes of interest; TLR4, MD-2, CD-14, MyD88, IL-6, IL-6R, CXCL2, CXCR1, and CXCR2." (PMID 35962138, 2022). "To that end, we isolated CD14+ TAMs from single-cell suspensions of primary human LUSC tumors, treated them with E-301 LOF or E-301, and cocultured them with autologous CD8 tumor-infiltrating lymphocytes (TILs)." (PMID 36322632, 2022). "These can also be identified in circulation and paired tumour and peritumour tissue samples with the co-expression of CD45, CD14 and EpCAM markers." (PMID 35884505, 2022). "Second, we defined a 21-gene tumor cDC2 subset-specific signature by comparison with blood cDC2 and tumor MMAC, CD14+ DC and pDC." (PMID 35418195, 2022). "Some well-known marker genes were used to identify cell types, such as EPCAM and KRT19 for tumor cell, COL1A1 and ACTA2 for CAF, CD3D and CD3E for T cell, and CD68 and CD14 for macrophage." (PMID 36499343, 2022). "Results indicated that among the four subgroups of MB, nine kinds of infiltrating immune cells (such as CD14, Regulatory T (Treg), CD58, CD8, and CD19) were statistically significant in the degree of tumor infiltration (p < 0.001)." (PMID 35967388, 2022). "CD14+ TGFBI+ M0‐like TAMs compose the greatest proportion of total TAMs and are related to tumor angiogenesis, hypoxic necrosis, and tumor necrosis factor signaling and PI3K–AKT signaling pathways." (PMID 35634956, 2022). "Since MDSCs play an important role in tumor maintenance, CD84 expression was determined on M-MDSCs (CD14+, CD11B+, HLA-DR–, CD15–) and granulocytic-MDSCs (G-MDSCs) (CD15+, CD11B+, HLA-DR–, CD14–) derived from BM patient samples." (PMID 33465053, 2021). "At the subset level, CD14+ MPs remained elevated in the tumor, and the percentage of CDC2 was significantly decreased in the tumor, along with a slight increase in CDC1." (PMID 34680397, 2021). "The transthoracic tumour biopsy revealed a tumour cell population with positivity for CD117, partially for CD14 and focally for CD45." (PMID 34382369, 2021). "The data demonstrates that the best performing immunotranscriptomic model is the one based on the CD14/CD2 ratio, emphasizing both the tumor phagocytosis mechanism and the anti-tumor immune response, yielded an AUC of 0.70." (PMID 34685549, 2021). "Gaining immune features (e.g., CD45, CD14, CD16) by cancer cells was recently described by the spontaneous fusion of tumor cells with macrophages to circulating hybrid cells." (PMID 34359649, 2021). "At the same time, the expression patterns of ZC3H12B, T cell markers CD4 and CD8, M1 type markers CD14 and CD86, and M2 type markers CD163 and CD206 were also detected in mouse tumor tissues." (PMID 33718596, 2021). "The prevalence of CD14+, CD68+ and CD163+ cells was higher in grade 3 tumors than in grade 1 tumors, both in PT Tumor and IT Tumor compartments." (PMID 34194435, 2021).
tumor (continued). "Evidence is furthered by looking at the tumor surrounding stroma where upregulation of STING and CD14 was observed in chemotherapy-only patients, suggesting a lack of positive immune infiltration in these patients." (PMID 34778231, 2021). "hrHPV+ tumors had higher infiltration rates of CD14+, CD68+ and CD163+ myeloid cells in the IT tumor compartment (p < 0.001, for all) compared to hrHPV− tumors." (PMID 34194435, 2021). "We also purified CD14+ monocytes from PBMCs of healthy volunteers to generate macrophages, and induced macrophages to TAMs using CM from ILT4-downregulated or control tumor cell lines." (PMID 33537094, 2021). "Our tumor MSCs expressed the following surface antigens: CD73, CD90, CD105, and HLA-class I ≥95% and CD34, CD14, CD45, CD31, and HLA-DR ≤ 5%." (PMID 34805051, 2021). "The number of CD14+ cells was also dependent on the TNM stage (p = 0.0444) and tumor budding (p = 0.0324)." (PMID 33625532, 2021). "When EMT decreases in CRC, CD14 + monocytes and CD19 + B cells also decrease, and the tumor increases infiltration of CD56 + NK cells." (PMID 34526059, 2021). "To confirm these results in a more pathophysiological setting, we generated tumor spheroids from MCF-7 control and MCF-7 miR-375 decoy cell lines 11 followed by infiltration with CD14+ human peripheral blood monocytes." (PMID 34158867, 2021). "hrHPV+ tumors had markedly higher numbers of CD14+, CD68+ and CD163+ myeloid cells in the intratumoral tumor (IT Tumor) compartment compared to hrHPV− tumors (p=0.001, p < 0.001, p=0.002, respectively)." (PMID 34194435, 2021). "As CD14+ MPs were the predominant MP subset, their inversed pattern of CD80 and PD-L1 expression in tumor and colon remained unchanged." (PMID 34680397, 2021). "The density of CD14+, CD68+, CD163+ cells in the intratumoral tumor (IT Tumor) compartment was significantly higher in hrHPV+ tumors than in hrHPV− tumors (p < 0.001, p < 0.001, p < 0.001, respectively)." (PMID 34194435, 2021). "We found that tumor-infiltrating CD33high cells showed high gene expression levels of CD36, CD14, FUT4 (CD15), CD80, CD86, CSF1R and immune checkpoint ligand genes including CD274 (PD-L1), LGALS9 (galectin-9), PVR and VSIR." (PMID 33000418, 2021). "Both mIgG4 or mIgG1 induced a significant reduction of CD14, CD163 and CD206 expression in M2a cells from healthy, primary tumor, and metastatic patients compared to unstimulated M2a controls." (PMID 33628623, 2021). "Several markers significantly correlated with CD3 expression in the tumour compartment, including CD40, CD44, CD14, B2M, Tim-3, CD8, CD45RO, and ICOS, potentially implicating other cell lineages in immune-associated anti-tumour activity." (PMID 33261133, 2020). "Remarkably, circulating class‐switched memory B cells (CD27+IgD−) showed a strong inverse correlation with CD68 staining grade, while intermediate monocytes (CD14++CD16+) negatively correlated with CD3+ and CD5+ cell density in the tumor." (PMID 33024560, 2020). "The values reflect the content of tumor-derived Apo10 and TKTL1 within CD14+CD16+ monocytes in peripheral blood." (PMID 32438648, 2020). "Three components of this proof of mechanism are the depletion of TAM from the tumor, a decrease of CD14 + CCR2+ IM in the peripheral blood, and the accumulation of CD14 + CCR2+ IM in bone marrow." (PMID 31297636, 2020). "Our results also showed that TAMs/monocytes (CD45+CD14+) were the main myeloid population in GCT, accounting for 2.2% of total tumor single cell suspension." (PMID 32814714, 2020). "We isolated the cells from neoplasm and compared different bio-markers (CD90, CD105, CD29, CD14, CD34, CD45) between three patients’ GCTSCs and normal bone marrow MSCs." (PMID 32904108, 2020). "CCR2 expression was detected on monocytic myeloid cells including CD14 monocytes and its myeloid precursors, whereas its specific ligand CCL2 (MCP1) is produced by tumor and stromal cells." (PMID 31811337, 2020).
tumor (continued). "In particular, GAD_CD14 derived gene signature indicates that the location of monocytic cells correlates with the distribution of TCF7 memory stem-like lymphocytes and tumor specific T cells." (PMID 33193316, 2020). "Consistently, RNAseq analysis of human cancers revealed a strong positive correlation between the expression of Treg markers (FOXP3, IL2RA) and myeloid cell markers (MRC1, CD14, and ITGAM) across several tumor types." (PMID 32782249, 2020). "We found relative expression of CD14 and CD68 to be downregulated in PBMCs and tumor-derived cells following incubation with KMP01D." (PMID 32425932, 2020). "Western blotting showed that E2F4 knockdown promoted the expression of CD11b and CD14 and inhibited the expression of cyclin D1, cyclin A2, P‐Rb and CDK4 compared with the expression in control tumours." (PMID 31943751, 2020). "Although we observed a drop of CD14 + CCR2+ IM in peripheral blood, a decrease of CCR2+ TAM in the tumor was only observed for two patients and is inadequate to support a definitive conclusion about this component of the mechanism of action." (PMID 31297636, 2020). "We also examined the relationship between IL-6 and PD-L1/PD-L2 positive CD45+CD14+ inflammatory cell (MO/MA) levels in three OC environments (TME): peripheral blood (PB), PF, and tumor (TT) and their clinical and prognostic relevance in OC patients." (PMID 33062717, 2020). "Conversely, we found GAD_CD14 derived signature being positively correlated with the expression of ITGAE (CD103) and TNFRSF9 (CD137) genes, which represent activated tumor-specific T-cells." (PMID 33193316, 2020). "What is interesting, the highest percentage of CD45+CD14+PD-L1+ and CD45+CD14+PD-L2+ was detected among the tumor-infiltrating cells." (PMID 33062717, 2020). "• For the whole tissue samples as well as for the tumor subregions, correlation coefficients for the CD163 staining are slightly larger than for CD14 staining for all surveyed methods." (PMID 31303867, 2019). "The mRNA induction in sorted CD14+ MΦ was manifold higher for CXCL10 and CCL2 as compared with tumor cells." (PMID 30850595, 2019). "Consistent with others, CD11b+CD14+ Mo-MDSC and Lin−HLA-DR−CD11b+CD15+ PMN-MDSC populations were much higher in patients with tumor as compared to tumor free-individuals." (PMID 31379854, 2019). "Because SR-A is a marker of differentiated macrophages, we compared the expression pattern of CD68, CD163, CD14 and SR-A in CHL tumor microenvironment." (PMID 31714922, 2019). "T cells and CD33 + CD14+ tumour-polarised MDSCs were co-cultured at a ratio of 1:0.5 and compared to CD33 + CD14+ monocytes." (PMID 31462392, 2019). "Namely, the presence of tumor infiltrating CD3+CD8+FoxP3− T cells, galectin-9+ dendritic cells (DC)/DC-like macrophages, a high CD14+CD163− (M1)/CD14+CD163+ (M2) macrophage ratio, and the expression of galectin-3 by tumor cells." (PMID 31248118, 2019). "We also measured CD14+ cell infiltration in 3D spheroids of ER + (MCF-7, T47D) and ER− (MDA-MB-468, MDA-MB-231) tumor cells." (PMID 30850595, 2019). "Two additional genes (CD14 and CSNK2A1) were dysregulated in MSS tumours and two genes (CARD11 and VCAM1) were downregulated and six genes were upregulated (LYN, TICAM2, ICAM1, IL1B, CCL4 and PTGS2) in MSI tumours." (PMID 29188362, 2018). "Altogether, our results support previous findings indicating that the tumour microenvironment induces the expression of PD-L1 in CD14+-TAMs, and that their interaction with CD4+PD-1+ cells triggers T-cell exhaustion, thus allowing tumour propagation." (PMID 30285662, 2018). "IDO-positive tumor- and stroma-infiltrating cells represented a heterogeneous population of immune cells consisting of HLA-DR−CD14+IDO+ MDSC-like cells, HLA-DR+CD14+IDO+ dendritic/macrophage-like cells, HLA-DR−CD14−IDO+-, and HLA-DR+CD14−IDO+ cells." (PMID 30050535, 2018).
tumor (continued). "Five genes, CACNB4 (FCMSS 0.65), MAP3K6 (FCMSS 0.66), CD14 (FCMSS 0.66), CACNA2D4 (FCMSS 0.66), and MAP4K4 (FCMSS 1.52) had slightly stronger FC for MSS-specific tumors than for all tumor combined (FCoverall 0.67, 0.73, 0.68, 0.67, and 1.47, respectively)." (PMID 29636593, 2018). "Here we show mechanisms of extravasation of human CD14dimCD16+ patrolling and CD14+CD16+ intermediate proangiogenic monocytes (HPMo), using human tumour xenograft models and live imaging of transmigration." (PMID 29367702, 2018). "MM tumor cells were purified using the Rosette Step MM purification kit, which removes other contaminating hematopoietic cells that contain CD2, CD14, CD33, CD41, CD45RA, CD66b markers and glycophorin A on red blood cells (RBCs)." (PMID 30383785, 2018). "A unique combination of biomarkers (CD11b, CD15, HLA-DR, CD14, LOX1, and S100A9) was developed to detect and quantify different populations of MDSC on a single FFPE tumor tissue section." (PMID 30400822, 2018). "TAMs are macrophages (characterized as F4/80+CD11b+Ly6Clow in mouse or CD11b+CD14+CD163+ in human) that accumulate in the tumor microenvironment and promote tumor progression." (PMID 30483271, 2018). "The F4/80+ TAMs present in these tumours represented 10.8 ± 3.3% of all live tumoural cells and expressed FAP, alongside the macrophage/TAM markers CCR2, CD11b, CD14, MHCII, IL4-R and MMR, with a low expression of the dendritic cell marker CD11c." (PMID 30054470, 2018). "Activatory FcγR expression was observed on tumor-infiltrating CD56+CD3− NK cells, CD11b+CD14+HLA−DR+ monocyte/macrophages (Mo/MΦs), and CD11b+CD15+CD14− granulocytes." (PMID 29576375, 2018). "In this case, the PD-L1 decoration involved only a small CD3 positive area that seemed to be enriched in CD14- and CD163-positive cells, which are known to contribute to the formation of a suppressive milieu and thus favour tumor escape." (PMID 28415643, 2017). "For example MAMPCs expressed mature macrophage markers such as CD14, CD36, CD64, and CD206 at comparable levels with MAMs, suggesting that MAMPCs have committed to a macrophage lineage in the tumor microenvironment." (PMID 29387063, 2017). "Finally, in the pro-inflammatory environment of tumor tissue, granulocytes may upregulate CD14." (PMID 28220123, 2017). "We confirmed that MAMPCs and MAMs in the metastatic lung expressed significantly higher levels of CD14, CD36, CD64 (Fcgr1), CD206 (Mrc1) and CCR5 proteins compared with circulating C-MOs in the tumor-bearing mice." (PMID 29387063, 2017). "FAP reduction decreased transcripts for IL-10, TGF-β, CCL5 and CCL22 from CD14+ cells, of which 20-40% were F4/80+ TAMs; CCL5 transcripts were also reduced in tumor cells." (PMID 26943036, 2016). "To address this possibility, we generated DCs from HCC tumour-isolated CD14+ monocytes (TMO-DCs) and paired blood CD14+ monocytes (BMO-DCs)." (PMID 27853178, 2016). "Levels of EpCAM+ tumor cells, CD45+ immune cells, CD45+/CD14+ MO/MA, and CD45+CD14+/CD16+ differentiated MO/MA were quantified by automated cell image analyses and compared between samples from miliary (n=6) and non-miliary (n=13) ascites." (PMID 27665539, 2016). "Our data indicated that circulating CD14+CD169+ M2-like monocytes and TIMs accumulated in the neoplasms and correlated with the levels of plasma IL-10 and CEA in CRC patients." (PMID 26509874, 2015). "The results indicate that high level of CD14, ARG1, and FOXP3 mRNA expression in primary NB tumor significantly correlated to a better survival." (PMID 26161395, 2015). "We found that the percentages of CD14+CD169+IL-10+ M2-like circulating monocytes and TIMs were significantly higher in CRC patients than in the HC or the non-tumor patients following in vitro activation." (PMID 26509874, 2015).
tumor (continued). "Our data suggest that an increase in the frequency of CD14+CD169+ cells may be associated with the development and progression of CRC and is concomitant rise of both, pro-tumor (M2-like, IL-10 producing) and anti-tumor (M1-like, IL-12 producing) monocytes and infiltrating macrophages." (PMID 26509874, 2015). "Tumor samples from mice subjected to daily restraint stress had elevated MCP1 gene and protein levels, increased CD14+ cells, and increased infiltration of CD68+ cells." (PMID 25738355, 2015). "In our study, CD14 levels were slightly, but significantly decreased after treatment with VALE and OA in both populations of tumour cell co-cultured MDM." (PMID 25902944, 2015). "Considering the mean quantile of expression versus other probes, surface markers CD64, CD1D, CD14, CD33, CD8A, CD16b, CD45 maintain a low level in cell lines versus microdissected tumor (all lower than the 35th quantile, p)." (PMID 25380171, 2014). "Using LPS-treated CD14-knockdown GC cells, these authors showed that CD14, an important co-receptor in the TLR4 complex, promotes tumor cell epithelial–mesenchymal transition and invasion through TNF-α." (PMID 25101079, 2014). "In conclusion, this is the first study to demonstrate that LPS effectively induces tumor growth in various experimental models of NSCLC in vitro, ex vivo and in vivo via CD14-, TLR4-, EGFR- and COX-2-signaling." (PMID 22923191, 2013). "This suggests CD14 is a key molecule in the rapid, earliest binding events of professional phagocytes and may have important implications for the function of circulating monocytes responding to material released from AC (e.g. from sites of apoptosis such as tumours and atherosclerotic plaques)." (PMID 23936239, 2013). "These CD14+ monocytes showed the ability to present recall antigens (PPD, Candida albicans) and neoantigens expressed on tumour cells and tumour-derived microvesicles (TMV) to autologous CD3+ T cells isolated from the peripheral blood." (PMID 23180014, 2013). "PBMCs were isolated from healthy volunteers and analyzed for CD14 and CD16 expression after 24 h of incubation with tumor cell supernatants." (PMID 22973451, 2012). "Following enzymatic digestion, tumor specimens were comprised of EpCAM+ tumors cells, and a CD45+ leukocyte population that contained CD14+ monocytes and CD3+ T cells, as well as a CD14- CD3- leukocyte subset." (PMID 21827675, 2011). "A recent study has documented that versican can activate tumour-infiltrating myeloid cells through TLR2 and its coreceptors TLR6 and CD14 and elicit the production of proinflammatory cytokines including TNF-α that enhance tumour metastasis." (PMID 20871832, 2010). "The pro-apoptotic CD14, TIA1, and ITGB2 were down-regulated in more than 50% of the tumor cultures after treatment with doxorubicin, as was the antiapoptotic YWHAH." (PMID 18959781, 2008). "This CEACAM recognition pattern of scFv E8 was also verified on a large panel of human cells which included 18 tumor cell lines, adult primary fibroblasts, PBMC subpopulations CD4 and CD14 and neutrophils." (PMID 16504122, 2006). "Notably, FCGR1A, CD14, and APOC1 emerged as key features within the model, with APOC1 also serving as a prominent marker for tumor-enriched macrophage subtypes." (PMID 41601657, 2026). "Fresh tumor samples were acquired from the University of Arizona biobanking facility and immediately dissociated and stained for markers of interest, namely CAIX, CD45, CD56, CD16 and CD14." (PMID 40440354, 2025). "In addition, regulatory DCs differentiated from CD14 + CD16 + monocytes can induce Th2 polarization, resulting in tumor immune tolerance." (PMID 39955339, 2025). "Increased proportions of postoperative CD33+CD14+ cells relative to preoperative levels were evident in patients without lymphatic tumor emboli." (PMID 39749673, 2025).